DDX3X (DEAD-box helicase 3 X-linked)
Diseases named in the same sentence as DDX3X in open-access papers (continued):
Sharing a sentence is not in itself a finding about the gene and the disease.
cancer (continued). "Together, these results suggest that drugs that limit SG assembly and/or promote stress granule disassembly might reverse translation defects caused by cancer-associated DDX3X mutations and potentially contribute treatment strategies for tumors that harbor DDX3X mutations." (PMID 27180681, 2016). "In several preclinical cancer models, small-molecule inhibitors like RK-33 have been demonstrated as antiproliferative due to their targeting of the Walker A motif of DDX3X and impairment of its ATPase function." (PMID 40564907, 2025). "While genetic alterations in DDX3X have been identified in several cancers, its role in cancer progression remains a subject of debate and varies depending on the cancer context." (PMID 40885716, 2025). "Its involvement in cancer biology has been extensively studied, with evidence suggesting that DDX3X promotes tumor progression in over ten types of cancers." (PMID 41198618, 2025). "Here, we investigated the regulation of DDX3Y by DDX3X in two male-derived human cancer cell lines, HCT116 and U87MG." (PMID 39975375, 2025). "Lastly, while our findings on EIF4A1 and DDX3X remain robust and underscore the potential importance of these RNA helicases in virus-positive tumors, they are derived from a limited number of cancer types." (PMID 40595559, 2025). "To assess the oncogenic relevance of DDX3X across malignancies and validate its potential as a target, we examined its expression profile in a pan-cancer context using TCGA data." (PMID 40564907, 2025). "Genome sequencing has identified numerous mutations in the DEAD‐box RNA helicases, DDX3X and DDX3Y, associated with cancer and other diseases, but monitoring of their functional consequences remains a challenge." (PMID 40385543, 2025). "This truncated form of DDX3X translocates and accumulates in the nucleus, triggering alternative RNA splicing that contributes to the adaptation of cancer cells to harsh microenvironments." (PMID 39851495, 2025). "A. javanica was selected for this study based on its traditional use in Unani and Ayurvedic medicine and its reported anticancer properties, making it a promising but understudied source of bioactive compounds targeting cancer-related proteins like DDX3X." (PMID 40564907, 2025). "This involvement in the β-catenin pathway was further mediated in a separate study examining multiple cancer lines and the effect of DDX3X depletion, as siRNA knockdown of DDX3X reduced cell motility and metastatic potential." (PMID 38539466, 2024). "Due to the protective nature of DDX3X during cellular stress, drug resistance can develop after cancer treatments." (PMID 38539466, 2024). "In this review, we have discussed the biological functions of DDX3X, as well as its pathological role in the development of cancer drug resistance." (PMID 38539466, 2024). "Second, DDX3X mediates multiple cellular signaling transductions, and some of these pathways can promote cancer progression and metastasis." (PMID 38539466, 2024). "Given its potential as a target for cancer treatment, extensive research attention has been devoted to DDX3X and its corresponding orthologs, resulting in the accumulation of a substantial amount of biochemical and biophysical information." (PMID 38316768, 2024). "In cancer cells, DDX3X was shown to globally repress protein synthesis while fostering the translation of specific RNAs by binding to the eIF4F complex." (PMID 38651369, 2024). "The authors further showed that this DDX3X nuclear fraction engages with splicing machinery to induce AS events in several cancer cells." (PMID 38299588, 2024). "Because of this, we will focus our discussion on the putative roles that DDX3X plays in drug resistance across cancer types." (PMID 38539466, 2024). "Further efforts should be put towards the development of DDX3X inhibitors or co-treatments as promising candidates for cancer therapies in the future." (PMID 38539466, 2024).
cancer (continued). "A bioinformatics analysis was undertaken to evaluate the expression levels of DDX3X in various types of cancer to determine its clinical significance in cancer progression." (PMID 38316768, 2024). "Further understanding of the mechanism behind DDX3X-mediated SGs is necessary to identify its role in drug resistance and uncover strategies for anti-cancer therapies." (PMID 38539466, 2024). "Owing to its diverse role in RNA metabolism, DDX3X has received growing interest of its role in cancer." (PMID 38609996, 2024). "DDX3X inhibitors have been shown to be successful in limiting the growth of several cancers and reducing DDX3X-mediated SG assembly." (PMID 38539466, 2024). "Overall, our discovery of the effect of AEP-cleaved DDX3X switching on alternative RNA splicing events identifies a mechanism in which cancer cells adapt to oxygen and nutrient shortages and provides potential diagnostic and/or therapeutic targets." (PMID 37988165, 2023). "The DEAD-box helicase family member DDX3X was one of the top candidates, as this protein that plays a vital role in cancer progression was revealed in both cell lines." (PMID 37845393, 2023). "DDX3X has also been identified as a somatic driver gene in several different cancers, with most compelling evidence in medulloblastoma." (PMID 38057330, 2023). "Here we characterise the functional consequence of over 12,000 DDX3X variants, using an improved SGE-based assay, to assess their relevance for NDDs and cancer." (PMID 38057330, 2023). "DDX3X is a mammalian RNA helicase that regulates RNA metabolism, cancers, innate immunity and several RNA viruses." (PMID 36725983, 2023). "AGR2 was found to trigger cancer metastasis in animal models, and the interaction of ATP-dependent RNA helicase DDX3X with AGR2 has been characterized at protein level." (PMID 37371098, 2023). "DDX3X is also known to be involved in modulating tumor proliferation, migration, invasion, and drug resistance in many types of cancer." (PMID 37834385, 2023). "Due to its complex biological role in RNA metabolism, ATP-dependent RNA helicase DDX3X has gained increasing attention for its function in many types of cancer, and it regulates tumor progression in a complex manner." (PMID 37371098, 2023). "Pathogenic variation in DDX3X, an X-linked gene encoding an RNA helicase, has been robustly associated with both neurodevelopmental disorders (NDD) and cancer (somatic mutations)." (PMID 38057330, 2023). "DDX3X downregulation and the decreases in ATP hydrolysis, inorganic phosphate release and cancer proliferation were reported." (PMID 37371098, 2023). "Remarkably, this dual role of DDX3X has been reported not only in different types of cancer but also in the same cancer." (PMID 35954483, 2022). "This revealed that few of the helicases are always lost across the cancers examined, such as DDX3X and DDX6." (PMID 36761420, 2022). "Loss-of-function mutations in DDX3Y result in male sterility, again suggesting a complex role for DDX3X/Y in cancer." (PMID 35626643, 2022). "Increased expression of its X homologue, DDX3X, has been reported in many cancer cells originating from somatic cells." (PMID 35624115, 2022). "A recent study demonstrated also that DDX3X physically interacts with estrogen receptor-alpha (ERα) and positively regulates its activity as a promoter of cancer progression." (PMID 35954483, 2022). "The involvement of DDX3X was also described for other types of cancers where it was mainly investigated as a biomarker for the prediction of survival." (PMID 35954483, 2022). "DEAD-box helicase 3 X-linked (DDX3) is a human RNA helicase that directly regulates m6A demethylase ALKBH5, thereby reducing m6A methylation of cancer stem cell transcription factor fork head box protein M1 (FOXM1) and Nanog, leading to chemoresistance." (PMID 36249071, 2022). "Six identified missense mutations of DDX3X increased the expression of AREG, suggesting a predominantly oncogenic role in this type of cancer." (PMID 35954483, 2022).
cancer (continued). "It does so without altering any specific phase, consistent with a study of DDX3X in cancer cells using FUCCI." (PMID 35762573, 2022). "Knockdown of DDX3X inhibited lung metastasis in BCa,19 and DDX3X promoted cancer cells survival by modulating mRNA metabolism, the stress response, hypoxia, apoptosis, and the cell cycle." (PMID 35811688, 2022). "Accumulating evidence indicates that DDX3X plays an essential role in embryonic development and cancer progression, modulating multiple biological processes, such as gene transcription, pre‐mRNA splicing, and protein translation." (PMID 35811688, 2022). "QRT–PCR analysis also showed that the expression of DDX3X was increased in cancer cells compared to that in human mammary epithelial cells." (PMID 35811688, 2022). "DDX3X has also been found to play a role in several forms of cancer, and dysregulation of its role in translation likely mediates at least some of its oncogenic properties." (PMID 36393867, 2022). "The involvement of DDX3X in miRNA biogenesis has been suggested for 14 types of cancer, including breast, colorectal, liver, squamous cell carcinoma, bladder, ovarian and acute myeloid leukemia, which were also found in our analysis." (PMID 35954483, 2022). "Many of these pathways are involved in different types of cancer, and DDX3X and DDX5 play a major role in their regulation." (PMID 35954483, 2022). "The correlation between DDX3X and Snail expression has been reported in different cancer types, and it is correlated with a poor prognosis." (PMID 34771731, 2021). "DDX3X is closely related to several of the hallmarks of cancer, including evading growth suppressors, resisting cell death, activating invasion and metastasis, promoting gene instability and mutation and deregulating cellular metabolism." (PMID 33627125, 2021). "Over two decades, many cohort studies in various cancers have investigated the expression level of DDX3X and its connection with the clinical characteristics of tumours." (PMID 33627125, 2021). "Then, we focus on the role of DDX3X in cancer biology and systematically demonstrate its functions in various aspects of tumorigenesis and development." (PMID 33627125, 2021). "In fact, DDX3X possesses numerous functions in cancer biology and is closely related to many well-known molecules." (PMID 33627125, 2021). "To provide a more intuitive understanding of the role of DDX3X in cancer, we summarized its functions and specific mechanisms in various types of cancer and presented its involvement in cancer-related signalling pathways." (PMID 33627125, 2021). "Numerous studies have uncovered the relationship between DDX3X and other functional proteins in cancer biology." (PMID 33627125, 2021). "Then, we focused on the role of DDX3X in cancer biology and systematically demonstrated its functions in various aspects of tumorigenesis and development." (PMID 33627125, 2021). "In LGG, genes such as CDKL5, KCND1, and DDX3X that have a role in different cancers have differential expression and methylation." (PMID 34621669, 2021). "To provide a more comprehensive understanding of its role in cancer, we summarized the role of DDX3X and the specific mechanisms in various types of cancer and presented its involvement in cancer-related signalling pathways." (PMID 33627125, 2021). "Noncanonical repressor DEAD-box RNA helicases (DDXs), such as DDX3X and DDX5, are also associated with the loss of E-cadherin in cancers, but DDX3X prefers to bind distal region of the E-cadherin promoter." (PMID 33608512, 2021). "We alternatively investigated the impact of DDX3X on RCC progression by a genome-wide analysis of differential gene expression in the Cancer Cell Line Encyclopedia (CCLE)." (PMID 32326089, 2020). "Although the impacts of DDX3X on many cancer types have been reported, the role of DDX3X in RCC remains largely obscure." (PMID 32326089, 2020).
cancer (continued). "Emerging evidence has further indicated the multibiological function of DDX3X in cancer cells; the oncogenic and tumor suppressive capability of DDX3X in regulating cancer proliferation, metastasis and drug resistance has been unraveled." (PMID 32326089, 2020). "Our results show that DDX3X is epigenetically repressed in RCC and that cancer patients displaying low DDX3X correlate with unfavored overall survival and tumor-node-metastasis (TNM) staging." (PMID 32326089, 2020). "Due to its complicated function in RNA metabolism, DDX3X has gained increasing attention for its biological functions in various types of cancers and has been shown to modulate cancer progression in a complex manner." (PMID 31906196, 2019). "Recently, the biomedical significance of DDX3X has been rapidly rising because it is closely related to cancer development and progression." (PMID 31300642, 2019). "DDX3X appears to regulate cancer proliferation and tumorigenesis, and both oncogenic and tumor suppressor roles have been uncovered." (PMID 31906196, 2019). "In this review, we focus on the biological function of DDX3X in cancer, and further illustrate its clinical significance on a pancancer scale." (PMID 31906196, 2019). "The relative expression of DDX3X in various cancer types demonstrates its pivotal role in tumor progression." (PMID 31906196, 2019). "In contrast, several studies have demonstrated a critical role for DDX3X in repressing cancer cell growth." (PMID 31906196, 2019). "All in all, these bioinformatics analysis data will pave us new avenues for thoroughly studying the biological functions of DDX3X-dependent miRNAs in cancers." (PMID 27586307, 2016). "In order to deeply study the potential roles of DDX3X-dependent miRNAs in cancers, we used various miRNA downstream targets prediction databases to screen the putative downstream targets of six DDX3X-dependent miRNAs." (PMID 27586307, 2016). "In this part, we used the primary data provided in the TCGA (The Cancer Genome Atlas) database to analyze the expression levels of DDX3X-dependent miRNAs in 14 kinds of cancers versus their adjacent normal tissues." (PMID 27586307, 2016). "Right now, there is rare study made on DDX3X and miRNA biogenesis, so in this article we will deeply discuss this novel mechanism and analyze its potential functions in cancer." (PMID 27586307, 2016). "And all these clinical expression data will provide us new directions and insights for exploring potential roles and biological functions of DDX3X-dependent miRNAs in different cancer types." (PMID 27586307, 2016). "We also identified frequent RNA helicase mutations (DDX3X and EIF4A1) in virus-positive tumors spanning multiple cancer types; although DDX3X mutations have been reported in HNSCC141, our results demonstrate their broader relevance across a pan-cancer cohort." (PMID 40595559, 2025). "Together, these results suggest that mutations in DDX3X and EIF4A1 may play a role in virus-positive tumors in various types of cancer." (PMID 40595559, 2025). "Because the extent of the response was lower in primary B cells compared to BL cells, our findings suggest that DDX3X inhibition could have broader applications in cancer therapy." (PMID 40772229, 2025). "In cancer, DDX3X can function as a tumor suppressor or as an oncogene depending on tumor type." (PMID 40385543, 2025). "In cancer cells, DDX3X and DDX3Y are redundant in the context of mRNA translation." (PMID 39444378, 2024). "Additionally, DDX3X inactivation with a small molecule inhibitor RK‐33 induces a global delay of cell‐cycle progression during interphase and mitosis and increases cancer cell death." (PMID 37975412, 2024). "Furthermore, an increasing body of evidence has suggested that dysregulation of DDX3X is commonly observed across different types of cancer." (PMID 38316768, 2024).
cancer (continued). "This implies that targeting the interaction between DDX3X and MYCN mRNA could potentially hinder the excessive protein synthesis and growth associated with these cancer cells." (PMID 37975412, 2024). "Altogether, DDX3X is a rising target for cancer therapeutics." (PMID 38539466, 2024). "It has been shown that targeting DDX3X inhibits mitochondrial translation, subsequently decreasing oxidative phosphorylation (OXPHOS) and increasing ROS production, causing metabolic disturbances in cancer cells and ultimately leading to cell death." (PMID 39701936, 2024). "DDX3X and its yeast ortholog Ded1 have functions related to eukaryotic translation initiation, stress response, immune response and brain development, and in this review, we focused on the dysregulation of these functions in the context of cancer." (PMID 39062517, 2024). "Finally, we discuss the relationships of DDX3X, SG, and cancer drug resistance, and discuss the current research progress of several DDX3X inhibitors for cancer treatment." (PMID 38539466, 2024). "Taken together, these studies indicate that high expression of DDX3X in certain cancer types may indicate more aggressive disease, meriting further investigation into DDX3X as both a biomarker of disease severity and an emerging therapeutic target." (PMID 38539466, 2024). "Based on the connections between DDX3X, SG formation, and cancer pathology, targeting DDX3X may be a promising direction for cancer therapeutics development." (PMID 38539466, 2024). "Pathogenic variants of DDX3X are associated with neurodevelopmental disorders (NDD) and cancer." (PMID 38057330, 2023). "Since DDX3Y is not expressed in normal human cells, these data suggest that DDX3Y may represent a new cancer cell specific target to develop adjuvant therapies for male patients with BL and DLBCL and LOF mutations in the DDX3X gene." (PMID 37035206, 2023). "ATP-dependent RNA helicase DDX3X, also known as DEAD (Asp-Glu-Ala-Asp) Box Polypeptide 3, X-Linked (DDX3X), is critical for RNA metabolism, and emerging evidence implicates ATP-dependent RNA helicase DDX3X’s participation in various cellular processes to modulate cancer progression." (PMID 37371098, 2023). "Hence, roles of ATP-dependent RNA helicase DDX3X in regulating cancer cell migration and invasion are proposed." (PMID 37371098, 2023). "Furthermore, ATP-dependent RNA helicase DDX3X has been proposed as a therapeutic target for cancers." (PMID 37371098, 2023). "Taken together, these data suggest that AEP-specific cleavage of DDX3X leads to nuclear translocation and that nuclear tDDX3X-C regulates oncogenic splicing in multiple kinds of malignant tumors, especially via PRDM2 and ARRB1, under tumor microenvironmental stimuli dependent on HIF1A." (PMID 37988165, 2023). "Recent evidence highlights the important functions of DDX3X in tumorigenesis and cancer progression, although it may play a tumor suppressive or an oncogenic role depending on the context of different cancers." (PMID 37845393, 2023). "In addition, mCAs involving loss of X chromosome affected DDX3X region, which is frequently altered in BL37, in 85% of BL cases compared to 55% of cancer-free children with mCAs on the X chromosome (~1.7%)." (PMID 38057307, 2023). "Therefore, I focused on ATP-dependent RNA helicase DDX3X’s biological effect on modulating cancer cell migration." (PMID 37371098, 2023). "Several studies have shown that DDX3X is a biomarker for good prognosis in cancers." (PMID 37834385, 2023). "I first considered DDX3X’s clinical significance in cancer patient cohorts." (PMID 37371098, 2023). "Hence, the conflicting roles of ATP-dependent RNA helicase DDX3X are inconsistent within the same type of cancer." (PMID 37371098, 2023).